TNFRSF10A (TNF receptor superfamily member 10a)
Diseases named in the same sentence as TNFRSF10A in open-access papers:
TNFRSF10A is named in the same sentence as 183 diseases in open-access papers, as found by Europe PMC text mining. Sharing a sentence is not in itself a finding about the gene and the disease. The quoted sentences say what the papers report.
breast carcinoma (70 papers, 2003 to 2025). "TNFRSF10A, the receptor for the cytotoxic ligand TNFSF10/TRAIL, can regulate apoptosis mediated by TRAIL; and inactivating mutations has been demonstrated to play a role in metastasis of breast cancer." (PMID 35159257, 2022). "Furthermore, curcumin can trigger TNFRSF10A-induced apoptosis in TNFRSF10A-resistant breast cancer cell lines via regulating apoptosis-related proteins such as MCL1, MAPK/ERK and AKT and genes such as MCL1." (PMID 36497321, 2022).
colon carcinoma (59 papers, 2003 to 2025). "Moreover, this compound and TNFRSF10A can function cooperatively against colon cancer HCT116 and HT-29 cells." (PMID 36497321, 2022).
lung carcinoma (23 papers, 2014 to 2025). "To determine the expression levels of EGFR and DR4/5 (TNFRSF10A/B) in lung cancers, we analyzed their transcriptional levels in the major 2 histological sub-types NSCLC and SCLC (small cell lung cancer; cancer cell line encyclopedia-TCGA database)." (PMID 37311043, 2023). "DDIT3 cooperates with KAT2A to up-regulate TNFRSF10A and TNFRSF10B expressions and to induce the endoplasmic reticulum stress-mediated apoptosis in lung cancer." (PMID 27931220, 2016).
pancreatic cancer (22 papers, 2003 to 2025). "We assessed the roles of LOC389641 and TNFRSF10A in the pancreatic cancer cell lines by forcing their overexpression or silencing and then culturing the cancer cells with SP." (PMID 35600049, 2022). "Our work could be used by researchers in the field of cancer biology and clinicians targeting TNFRSF10A/TRAILR1 in pancreatic cancer." (PMID 40424767, 2025). "Our present study, for the first time, revealed the roles played SP/NK-1R and LOC389641/TNFRSF10A in the PNI of pancreatic cancer cells and might provide some novel biomarkers for monitoring the effect of pancreatic cancer therapy." (PMID 35600049, 2022). "We speculate that the pancreatic cancer PNI process promoted by the SP/NK-1R axis can be blocked by the TNFRSF10A/NF-κB pathway mediated by LOC389641." (PMID 35600049, 2022). "However, either the overexpression or silencing of LOC389641 changed the effect of SP stimulation on pancreatic cancer PNI by regulating TNFRSF10A." (PMID 35600049, 2022). "Therefore, we assumed that pancreatic cancer PNI process promoted by the SP/NK-1R axis could be blocked by the TNFRSF10A/NF-κB pathway mediated by LOC389641." (PMID 35600049, 2022). "Moreover, we found that pancreatic cancer PNI promoted by the SP/NK-1R axis could be blocked by the TNFRSF10A/NF-κB pathway mediated by LOC389641." (PMID 35600049, 2022). "TNFRSF10A was the target gene of LOC389641, which is believed to be one of the lncRNAs that regulates the metastasis of pancreatic cancer cells." (PMID 35600049, 2022). "Taken together, these data showed that either overexpression or silencing of LOC389641 could change the effect of SP stimulation on pancreatic cancer PNI, and the effect might occur by altering TNFRSF10A expression." (PMID 35600049, 2022).
ovarian carcinoma (21 papers, 2009 to 2024). A malignant neoplasm originating from the surface ovarian epithelium. "Several genes silenced by promoter DNA hypermethylation such as MLH1, SULF1, SFRP, TNFRSF10A, UCHL1, and CLDN4 are related to platinum resistance in ovarian cancer." (PMID 33680048, 2020).
prostate carcinoma (18 papers, 2010 to 2025). A carcinoma that arises from epithelial cells of the prostate gland. "Curcumin was reported to increase the susceptibility of prostate cancer LNCaP cells to TNFRSF10A by inhibiting NFKB stimulation through hindering phosphorylation of NFKBIA/IκBα and its degradation." (PMID 36497321, 2022). "The upregulated TNFRSF10A can mediate cell cycle arrest, anti-proliferative and apoptotic effects, which is consistent with previous findings in prostate cancer cell line studies." (PMID 35631261, 2022). "In 2006, an investigation reported that TNFRSF10A/TRAIL-induced apoptosis is increased by quercetin via AKT dephosphorylation and activation of caspases in human prostate cancer LNCaP and DU-145 cells." (PMID 36497321, 2022).
gastric cancer (12 papers, 2017 to 2024). A primary or metastatic malignant neoplasm involving the stomach. "In this study we found that the expression of DR5 (TRAILR2, TNFRSF10B) presented a malignant phenotype as an independent risk factor for poor prognosis in gastric cancer patients, which was different from DR4 (TRAILR1, TNFRSF10A)." (PMID 37879960, 2023).
autoimmune disease (9 papers, 2006 to 2025). A disorder resulting from loss of function or tissue destruction of an organ or multiple organs, arising from humoral or cellular immune responses of the individual to their own tissue constituents. "The genes harboring these mutations, including DGKI, TNFRSF10A, GNGT1, CPAMD8, and BAFF, which are expressed in both eye and brain tissues and/or are related to autoimmune diseases, provide new avenues to evaluate the inherited causes of these devastating autoimmune conditions." (PMID 31161422, 2019).
bladder cancer (8 papers, 2012 to 2024). "The expression of TNFRSF10A and TNFRSF10B was further enhanced by combinatorial treatment, suggesting that apoptosis‐related genes were involved in the regulation of proliferation of bladder cancer cells with melatonin and/or VPA." (PMID 28593135, 2017).
cholangiocarcinoma (7 papers, 2016 to 2023). A carcinoma that arises from the intrahepatic biliary tree (intrahepatic cholangiocarcinoma) or from the junction, or adjacent to the junction, of the right and left hepatic ducts (hilar cholangiocarcinoma). "This altogether suggests a possible important role of a T-cell-/NK-cell/monocyte-mediated TRAIL-R1/TNFRSF10A-dependent anti-tumor activity in cholangiocarcinoma." (PMID 37404757, 2023). "Finally, an anti-tumor activity of TRAIL/TNFSF10 in cholangiocarcinoma can also rely on additional mechanisms, namely activation of other TRAIL receptors than TRAIL-R1/TNFRSF10A, and targeting of other tumor promoting cells than just the tumor cells." (PMID 37404757, 2023).
viral infection (7 papers, 2006 to 2024). "Additional proviral hits CDKN1A (p21) and TNFRSF10A, ISGs with antiproliferative and/or proapoptotic effects, were depleted upon Dox treatment independently of viral infection, and were further depleted by SARS-CoV-2 infection." (PMID 35421191, 2022).
pancreatic ductal adenocarcinoma (6 papers, 2016 to 2025). An infiltrating adenocarcinoma that arises from the epithelial cells of the pancreas. "Cytoplasmic TNFRSF10A has been considered to be a positive prognostic marker in pancreatic ductal adenocarcinoma, and the TNFRSF10A gene is involved in the NF-κB signaling pathway." (PMID 35600049, 2022). "LOC389641 was reported to promote pancreatic ductal adenocarcinoma progression and increase cell invasion by regulating E-cadherin, with the possible involvement of TNFRSF10A." (PMID 35600049, 2022). "Moreover, LOC389641 promotes progression of pancreatic ductal adenocarcinoma and increases cell invasion by regulating E-cadherin with the possible involvement of TNFRSF10A." (PMID 27708234, 2016). "LOC389641 was reported to promote pancreatic ductal adenocarcinoma progression and increase cell invasion by regulating E-cadherin, with the possible involvement of tumor necrosis factor receptor SF10A (TNFRSF10A)." (PMID 35600049, 2022).
age-related macular degeneration (4 papers, 2013 to 2025). Age-related loss of vision in the central portion of the retina (macula), secondary to retinal degeneration. "Our data showed that the risk allele for age-related macular degeneration is linked to increased TNFRSF10A expression compared to the opposite allele." (PMID 37277347, 2023). "Finally, a reQTL that was linked to a risk SNP for age-related macular degeneration was found to regulate TNFRSF10A gene expression." (PMID 37277347, 2023). "Additionally, dysregulation of TNFRSF10A is linked to age-related macular degeneration in humans." (PMID 40568085, 2025). "For age-related macular degeneration we found strong colocalization for TNFRSF10A in monocytes following 6h exposure to N. meningitidis or S. aureus (H4,Nm > 0.999, H4,Sa > 0.999)." (PMID 37277347, 2023). "Notably SNP rs13278062 at 8p21.1, associated with exudative age-related macular degeneration (AMD) in the Japanese population, was reported to alter the transcriptional levels of TNFRSF10A (Tumor necrosis factor receptor superfamily 10A) protein-coding gene." (PMID 23341781, 2013).
COVID-19 (4 papers, 2021 to 2025). A disease caused by infection with severe acute respiratory syndrome coronavirus 2. "Furthermore, expression levels of genes controlling cell proliferation and apoptosis, such as TGFB1, CDK4, TNFSF10, and TNFRSF10A, were also found to be dysregulated in CD4+ T cells of patients who recovered from COVID-19." (PMID 34784300, 2021).
osteosarcoma (4 papers, 2010 to 2024). A usually aggressive malignant bone-forming mesenchymal neoplasm, predominantly affecting adolescents and young adults. "Interestingly, in our recent study we showed that DOCK5 is located in the most significant region of copy number loss in osteosarcoma 8p21.2-p21.3 along with the TNFRSF10A gene, for which we see an overall trend of loss of expression in our current study." (PMID 20465837, 2010).
Obesity (3 papers, 2012 to 2022). Accumulation of substantial excess body fat. "Other BMs revealed to be associated with obesity-related HF are suggestive of mechanisms associated with apoptosis (TNFRSF10A), inflammation (ST6GAL1 and GAL-9) and fibrosis (MMP12, TIMP1 and QPCT)." (PMID 35945262, 2022). "Regarding the association between TNFRSF13B, TNFRSF10A, and type II diabetes mellitus, our results support previous findings of TNF-α being linked to obesity and insulin resistance." (PMID 35211520, 2022).
multiple sclerosis (2 papers, 2014 to 2023). A progressive autoimmune disorder affecting the central nervous system resulting in demyelination. "In particular, people with multiple sclerosis on natalizumab had lower CD6, CDCP1, CXCL13, CXCL9, NfL, TNFRSF10a, TNFSF13B and VCAN (P < 0.036)." (PMID 37361716, 2023).
schizophrenia (2 papers, 2024 to 2026). A major psychotic disorder characterized by abnormalities in the perception or expression of reality. "The role of TWEAKR (TNFRSF12A) has not been widely explored in psychiatric disorders, and to our knowledge, this is the first study to find significantly increased DR4 (TNFRSF10A) mRNA in high-inflammation schizophrenia and bipolar postmortem brains." (PMID 41567988, 2026). "We found multiple TNFSF receptor transcripts increased in high-inflammation schizophrenia cases compared with low-inflammation controls, including TNFRSF1A (log2 fold change [FC] = 0.91, adjusted p [p adj.] = 1.93 × 10−10, +87.44% increase), TNFRSF10A (log2FC = 0.56, p adj." (PMID 41567988, 2026).
acute coronary syndrome (1 paper, 2022). Signs and symptoms related to acute ischemia of the myocardium secondary to coronary artery disease. "A previous study has identified TNFRSF10A as predictor of recurrent acute events in patients with a history of acute coronary syndromes, while in another study TNFRSF10A was associated with the presence of high-risk coronary atherosclerotic plaques on computed tomography angiography." (PMID 35211520, 2022).
anorexia nervosa (1 paper, 2020). A disorder most often seen in adolescent females characterized by a refusal to maintain a minimally normal body weight, an intense fear of gaining weight, a disturbance in body image, and, in postmenarcheal females, the development of amenorrhea. "Across the four anorexia nervosa associated gene sets, four genes overlap between the Lutter damaging variants and Negraes iPSC derived gene set (TNFRSF10A, SCGB1A1, IFIT3, and GIPC3; hypergeometric test, p < 0.02)." (PMID 32651428, 2020).
atherosclerosis (1 paper, 2022). A disease characterized by the build-up of fatty material and calcium deposition in the arterial wall resulting in partial or complete occlusion of the arterial lumen. "Although, the debate is currently ongoing regarding the importance of TNFRSF10A as a predictor for atherosclerosis progression, our results come to support the accumulated past evidence." (PMID 35211520, 2022).
avian influenza (1 paper, 2018). Infection of domestic and wild fowl and other birds with influenza A virus. "However, expression of TNFSF10 and TNFRSF10a genes was significantly higher in cells transfected with PB1-F2 of highly pathogenic avian influenza-H5N1-WB virus." (PMID 30687405, 2018).
falciparum malaria (1 paper, 2013). "Other important components of THαβ immune response included up-regulation of HMOX1, FAS, BCL6, TNFRSF10A, and MIP1α were noted in Griffiths’ research, which studied the peripheral blood leukocytes from Kenyan children with acute falciparum malaria." (PMID 24188121, 2013).
migraine (1 paper, 2024). "The MR analysis of eQTL data showed that four drug targets (PROCR, GSTM4, SLC4A1, and TNFRSF10A) were significantly associated with migraine risk in both the FinnGen and UK Biobank cohorts." (PMID 39039470, 2024).
nasopharyngeal carcinoma (1 paper, 2025). A carcinoma arising from the nasopharyngeal epithelium. "Conversely, reducing FOLR1 levels alters key apoptotic and MAPK pathway genes (BIRC3, caspases, FOS, DUSP1, PRKX, TNFRSF10A), sensitizing taxol-resistant nasopharyngeal carcinoma cells to chemotherapy." (PMID 41439026, 2025).
cancer (325 papers, 2003 to 2026). A tumor composed of atypical neoplastic, often pleomorphic cells that invade other tissues. "In contrast to healthy breast cells, low TNFRSF10A expression in various types of cancer, including BC, is associated with decreased apoptosis and cancer cell enhancement." (PMID 35631261, 2022). "We identified TNFRSF10A/TRAILR1 as a promising target at the intersection of cancer cell apoptosis and the immunosuppressive microenvironment." (PMID 40424767, 2025). "TNFRSF10A is traditionally known as pro-apoptotic, meaning most studies in other cancers focused on an agonist approach." (PMID 40424767, 2025). "Cancer cells within the PDAC microenvironment exhibit aberrantly elevated TNFRSF10A expression." (PMID 40424767, 2025). "TNFRSF10A (TRAIL-R1) is an apoptosis-inducing receptor for the tumor necrosis factor-related apoptosis-inducing ligand (TRAIL) which is a potent inducer of apoptosis in many cancer cells." (PMID 20626868, 2010). "DR4 (TNFRSF10A) and DR5 (TNFRSF10B) bind TRAIL and TNFα and can trigger cell death primarily in cancer cells." (PMID 34069424, 2021). "We further investigated the expression of alternative genes through which T cells can induce cytolysis of cancer cells, including CD95-CD95L (FAS-FASLG) and TRAIL-TRAILR (TNFSF10, TNFRSF10A/B)." (PMID 29515971, 2018). "A total of 8 cancer genes with an OncoScore above the 90th percentile was identified (TNFRSF10B, TNFRSF10C, TNFRSF10A, TNFRSF10D, LZTS1, NKX3-1, BNIP3L and RHOBTB2; OncoScore range: 71.4–86.3)." (PMID 28387367, 2017). "Conversely, some genes that displayed anti-HIV activity are known to be involved in signaling, both in various cancers (CD164, TNFRSF10A/D, ZWINT, MT1X, IL3) and immune or T cell activation (GBP5, CD1A)." (PMID 25980612, 2015). "Therefore, we hypothesize that targeting the TNFRSF10A in PDAC could bypass some resistance mechanisms and directly induce cancer death even without a robust T-cell response." (PMID 40424767, 2025).
tumor (293 papers, 2003 to 2026). "In PDAC, higher TNFRSF10A expressions in the CAFs and tumor cells are associated with apoptotic resistance and enhanced tumor aggressiveness, immunosuppression, and metastatic capability." (PMID 40424767, 2025). "MYC, BMP2, and FOS show an associative trend when overexpressed, and TNFRSF10A shows a trend in underexpression in the tumor cohort." (PMID 20465837, 2010). "The integration of the single-cell angle showed us that TNFRSF10A is principally expressed in malignant epithelial cells, along with a set of stromal cells (supposedly activated fibroblasts) on the stromal-tumor interface." (PMID 40424767, 2025). "In CAF-rich regions, TNFRSF10A mRNA levels were two to three times higher than in immune-suppressive regions (p = 0.004), and hypoxic tumor zones also showed elevated TNFRSF10A (1.8-fold above immune-suppressive regions)." (PMID 40424767, 2025). "In the case of PDAC specifically, high expression of TNFRSF10A might enhance tumor survival, migration, immune suppression, or resistance to chemotherapy." (PMID 40424767, 2025). "Therefore, TNFRSF10A signaling can paradoxically stimulate the pro-survival NF-ΚB pathway and inflammation-driven tumor progressions." (PMID 40424767, 2025). "Monoallelic deletion of TRAIL-R1/2 (TNFRSF10A/B, also called death receptor 4/5 (DR4/DR5)) can antagonize TRAIL-induced apoptosis in B-NHL18, suggesting that TRAIL-R1/2 may function as tumour suppressors." (PMID 27199251, 2016). "In both datasets, expression of TRAIL and TRAIL-R1/TNFRSF10A was higher in malignant cells, compared to the average of other cell types in tumor and surrounding liver tissue." (PMID 37404757, 2023). "Comparison between the pairs of primary and recurrent tumor samples revealed that 5 genes were concordantly upregulated with a > twofold difference in expression level, including BCL10, BIRC3, CD40, TNFRSF10A and TRAF4." (PMID 34488754, 2021). "Due to the tumor-specific cytotoxicity of TRAIL, its recombinant version and agonistic antibodies against the death-inducing TRAIL receptors (TNFRSF10A/DR4, TNFRSF10B/DR5) are currently being tested in Phase I/II clinical trials." (PMID 25527049, 2014). "In HNSCC cell lines, FADD expression was higher in HPV(−) tumor lines, and TNFRSF10A/B/C exhibited decreased expression in HNSCC compared to normal human oral keratinocyte lines (HOK)." (PMID 33737574, 2021).
TNFRSF10A also shares sentences with these, for which no sentence is quoted: melanoma (30 papers); colorectal cancer (22); infection (21); hepatocellular carcinoma (20); glioblastoma (18); leukemia (15); type 1 diabetes (15); glioma (13); non-small cell lung carcinoma (11); myeloma (9); Arthritis (8); Autoimmunity (7); cervical carcinoma (7); chronic lymphocytic leukemia (7); diabetes (7); neuroblastoma (7); rheumatoid arthritis (7); oral cancer (6); adenocarcinoma (5); colorectal tumor (5); lymphoma (5); renal carcinoma (5); hematological malignancies (4); liver cancer (4); adenoma (3); autism (3); B cell lymphoma (3); invasive ductal carcinoma (3); kidney cancer (3); lung adenocarcinoma (3).
A further 126 diseases each share a sentence with TNFRSF10A in 3 papers or fewer.